CRP (C-reactive protein)
Diseases named in the same sentence as CRP in open-access papers (continued):
Sharing a sentence is not in itself a finding about the gene and the disease.
tuberculosis (continued). "In conclusion our data indicate that CRP could have a role in sub-Saharan Africa in the evaluation of tuberculosis suspects who are sputum smear-negative." (PMID 21249220, 2011). "The differential model of TBM and non-TBM was composed of the systemic symptoms of tuberculosis, altered consciousness, neurological deficits, meningeal irritation, cerebrospinal fluid protein, positive T-cell spot test for tuberculosis infection, and C-reactive protein." (PMID 41313026, 2026). "In the present study, we found that inflammatory mediators, especially IFN-γ, CRP, and total sialic acid measured collectively, may be useful for evaluating the systemic inflammatory response in subjects with APTB and TBDM before and after anti-tuberculosis treatment." (PMID 38562330, 2024). "Finally, monitoring sputum smear microscopy results alongside the determination of proposed inflammatory mediators (IFN-γ, CRP, and total sialic acid) are effective in evaluating the response to anti-tuberculosis treatment in APTB subjects without DM, warranting further investigation." (PMID 38562330, 2024). "There is also a possible bias due to participants with previous tuberculosis who were Xpert Ultra–positive and culture-negative, as this may have led to overestimating sensitivity and underestimating specificity of CAD4TBv7, but not CRP." (PMID 39190813, 2024). "CRP was correlated poorly with anti-A60 antibodies, while anti-A60 IgA and IgG were correlated in non-tuberculosis (TB) and SPCP patients (p < 0.001)." (PMID 30935095, 2019). "Thus, serum copper and CRP concentrations may be important parameters for evaluating the persistence of nonconversion after one month of tuberculosis treatment." (PMID 26197334, 2015). "At the last follow-up, there was no recurrence of tuberculosis in both groups, and ESR and CRP returned to normal." (PMID 36419079, 2022). "There was no signs of active tuberculosis in the brain or other organs and inflammatory markers [erythrocyte sedimentation rate (ESR) and C-reactive protein (CRP)] were in normal range." (PMID 31749937, 2019). "C-reactive protein (CRP) is a non-specific acute phase serum protein that is elevated in HIV seropositive and seronegative patients with tuberculosis." (PMID 21249220, 2011). "C-reactive protein (CRP) is a non-specific inflammatory marker that has been found to be elevated in both HIV-infected and uninfected people with pyogenic infections including active tuberculosis." (PMID 35806852, 2022). "The median CRP quotient was not affected by previous treatment for tuberculosis in the 135 participants with confirmed tuberculosis (16.5 [IQR 11.4; 21.2] and 14.2 [IQR 7.1; 23.4] in the participants with and without prior tuberculosis respectively, p = 0.58)." (PMID 21249220, 2011). "Importantly, the CRP quotient was not affected by HIV status, and in HIV seropositive participants with confirmed tuberculosis was significantly higher in those with advanced HIV disease." (PMID 21249220, 2011). "Similarly, although plasma-CRP was elevated in most patients, there were cases presenting with values as low as 2.5 in the EBV group and < 2 mg/l among the tuberculosis and neuroborreliosis groups, providing no clear evidence of on-going infection." (PMID 20626864, 2010).
inflammatory bowel disease (195 papers, 2007 to 2025). A spectrum of small and large bowel inflammatory diseases of unknown etiology. "A study of over 100 000 individuals showed a significant increase in serum CRP levels in inflammatory bowel disease patients and with that an increased risk for atherosclerotic CVD." (PMID 39494478, 2024). "DNAm site TMEM49-cg16936953 was also associated with HIV infection, C-reactive protein and inflammatory bowel disease." (PMID 36303554, 2022). "In inflammatory bowel disease patients, three single nucleotide polymorphisms (rs1205, rs1130864, and rs1417938) showed association with elevated CRP levels at diagnosis." (PMID 35327530, 2022). "C-reactive protein, another marker of inflammation that can be used in determining the activity of inflammatory bowel disease, was assessed in the study, as well as its association with disease relapse." (PMID 33396524, 2020). "It is well-known that a CRP test could be used to monitor conditions that cause inflammation, including bacterial infections, fungal infections and inflammatory bowel diseases." (PMID 34571946, 2021). "Inflammatory bowel disease is associated with elevated salivary IL-6 and CRP." (PMID 24915044, 2014). "Of interest, the decreased methylation level of these two loci was also strongly associated with higher CRP concentrations and higher risk of inflammatory bowel disease (IBD) in previous EWAS studies." (PMID 33499918, 2021). "Besides CRP, IL-6 was closely monitored due to the association with inflammatory bowel disease." (PMID 32188047, 2020). "Serum C-reactive protein (CRP) is a well-established systemic marker of inflammation widely used in inflammatory bowel disease (IBD) management." (PMID 40667420, 2025). "Initial investigations, including elevated CRP and fecal calprotectin, suggested inflammatory bowel disease, and treatment was initiated accordingly." (PMID 40823575, 2025). "This is consistent with the fact that inflammatory bowel diseases are chronic inflammatory conditions that contribute to elevated CRP levels." (PMID 39940324, 2025). "In conclusion, C-reactive protein plays a pivotal role in the evaluation and management of inflammatory bowel disease." (PMID 39062093, 2024). "At week 13, we assessed the patients with colonoscopy, the Harvey Bradshaw Index (HBI), the Inflammatory Bowel disease Health Related Quality of Life Questionnaire, and the measurement of serum C-reactive protein and fecal calprotectin (FC) levels." (PMID 39458148, 2024). "In our study, the typical butyrate producing bacteria Roseburia was reduced and negatively correlated with the serum level of CRP, which is consistent with the study of inflammatory bowel disease." (PMID 37692165, 2023). "Other reasons included reduced range of motion (65%), morning stiffness/tiredness (56%), elevated erythrocyte sedimentation rate/C-reactive protein level (47%), nail changes (41%), uveitis (24%), fatigue (15%), and inflammatory bowel disease (15%)." (PMID 37194936, 2023). "Fecal calprotectin is a non-invasive biomarker that assesses intestinal inflammation and is a more sensitive marker than CRP for detecting inflammatory bowel disease activity." (PMID 36895716, 2023). "Laboratory markers such as white blood cells, C reactive protein, and erythrocyte sedimentation rate can aid in assessing the activity of inflammatory bowel disease but lacks sensitivity and specificity." (PMID 36098358, 2022). "The CRP and FC are good biomarkers for any inflammatory bowel disease, including CD, and a reduction/normalization in their levels implies better clinical response and disease control." (PMID 36362709, 2022). "In patients with inflammatory bowel disease, an increase in CRP concentration has been reported as a good correlation with the clinical activity of the disease." (PMID 35635011, 2022).
inflammatory bowel disease (continued). "In a recent study in patients with inflammatory bowel disease, a positive correlation between U-II and high sensitivity C-reactive protein, a well-established biomarker of low-grade inflammation, has been observed." (PMID 35204924, 2022). "A prospective observational study revealed that the optimal cutoff for TLI associated with CR and CRP normalization was 2.1 μg/ml, while that for TLI associated with CR with normal CRP and fecal calprotectin (<50 μg/g) was 4.9 μg/ml in adults with inflammatory bowel disease (IBD)." (PMID 34966700, 2021). "As with Rome IV, many clinicians would also choose to conduct baseline blood tests (including C-reactive protein) and stool tests (including fecal calprotectin and culture) for exclusion of infections, celiac disease, and inflammatory bowel disease." (PMID 30908308, 2019). "The most widely acknowledged inflammation markers for monitoring chronic and acute disease activity in inflammatory bowel disease (IBD) are C‐reactive protein (CRP), an acute phase protein with a short half-life and total white blood cell count." (PMID 29435759, 2018). "Patients with CD have a higher CRP production compared with patients with other inflammatory bowel disease, and in CD, CRP level correlated well with disease activity." (PMID 26200619, 2015). "A pilot study reported curcumin clinically improved patients with inflammatory bowel disease in addition to decrease of sedimentation rate and CRP level." (PMID 25901155, 2015). "Biomarkers such as CRP, fecal calprotectin, and fecal lactoferrin have been reported to act as surrogate markers of mucosal inflammation in patients with inflammatory bowel disease, with CRP being a particularly sensitive marker in UC patients." (PMID 24758588, 2014). "Arecent study done on Inflammatory Bowel disease has deciphered the beneficial role of LRG compared to the other biomarkers indetermining the disease activity thereby denoting LRG as a promising surrogate for CRP." (PMID 40822769, 2025). "FC is a specific marker for intestinal mucosal inflammation and is routinely measured in stool samples, while CRP and interleukin-6 (IL-6) are nonspecific markers of inflammation associated with inflammatory bowel disease–related inflammation." (PMID 40831567, 2025). "Serum and fecal biomarkers, such as c-reactive protein and calprotectin, may also help exclude inflammatory bowel disease (IBD) in patients with low overall clinical suspicion for IBD who present with irritable bowel features." (PMID 40507697, 2025). "I think the only times I would use it is if I thought that the child had some kind of inflammatory condition, like an inflammatory arthritis or inflammatory bowel disease, where the CRP would really help with the diagnosis, because otherwise it’s an extremely vague marker." (PMID 38499294, 2024). "Although inflammatory bowel disease was quiescent or mild, CRP levels increased." (PMID 39093772, 2024). "CRP is an acute phase protein synthesized by hepatocytes in response to inflammatory stimuli such as microbial invasion or tissue damage, which can be used as a marker to evaluate the activity of inflammatory bowel diseases (Sands, 2915)." (PMID 38881869, 2024). "It is worth mentioning that despite being a more expensive test and not providing a definitive diagnosis for either of the diseases studied by us, calprotectin is a more specific parameter for inflammatory bowel diseases and shows a higher correlation with them than CRP." (PMID 39457188, 2024). "Similarly, inflammatory bowel disease (IBD), as a common intestinal disease, is also associated with increased CRP and other inflammatory mediators." (PMID 39574525, 2024). "In addition, in patients with inflammatory bowel disease (IBD), hs‐CRP was also significantly inversely associated with free thiols." (PMID 32558346, 2020).
inflammatory bowel disease (continued). "Traditionally measured in feces in inflammatory bowel disease diagnostics, calprotectin differs from hepatocyte-dependent acute-phase reactants like C-reactive protein (CRP) and erythrocyte sedimentation rate (ESR) because it is locally released by leukocytes at the sites of inflammation." (PMID 31805992, 2019). "The accuracy of the device (as characterized by the area under the receiver operator characteristics curve) is 89% and 83% for cut-offs of 10 ng/mL (for neonatal sepsis and pelvic inflammatory disease) and 30 ng/mL (for inflammatory bowel diseases) CRP in 1000-fold diluted blood respectively." (PMID 28738231, 2018). "While these CP-related findings differ from intestinal CD, we could detect a higher abundance of predictive protein markers for anti-TNF-α therapy in CD esophagitis as described in serum of inflammatory bowel disease (IBD) patients such as CRP, ITGAV, APOE, and CLU (Fig. EV4C)." (PMID 39901020, 2025). "For example, a proof‐of‐concept clinical study was conducted on patients with inflammatory bowel disease (IBD) to measure CRP levels using a skin‐mounted microfluidic patch." (PMID 39588557, 2025). "C-reactive protein (CRP), which is released by hepatocytes upon stimulation of pro-inflammatory cytokines, is associated with inflammatory bowel disease (IBD)." (PMID 39865190, 2025). "Many patients with inflammatory bowel disease (IBD) in clinical remission with normal CRP levels still have active on-going colonic inflammation, reflected by increased FC." (PMID 39274360, 2024). "In three studies investigating inflammatory bowel disease (IBD), the plasma C-reactive protein (CRP) level was examined as a specific marker for the GLIM etiological criteria of inflammation, wheras other studies only provide a broad definition." (PMID 37736137, 2023). "Their analysis is superior to serological tests (e.g., ESR and CRP) for differentiating inflammatory bowel disease (IBD) from IBS." (PMID 37242178, 2023). "Periodic and regular CRP level measurement is a potent and advantageous technique for gauging the success of therapeutic strategies for inflammatory bowel disease (IBD)." (PMID 39554800, 2023). "Some studies have shown an association between C-reactive protein (CRP)-albumin ratio (CAR) and prognosis in patients with inflammatory bowel disease (IBD), but evidence regarding the association between CAR and UC remains limited." (PMID 35094678, 2022). "Comment: Erythrocyte sedimentation rate (ESR) and C-reactive protein (CRP) measurements have been used to identify patients with inflammatory bowel disease (IBD)." (PMID 33538894, 2021). "The patient declined to undergo colonoscopy, therefore based on the result of the CT scan, laboratory tests (C-reactive protein 149 mg/L) and the symptoms, inflammatory bowel disease (IBD) was diagnosed." (PMID 33832425, 2021). "The aims of this study were to evaluate the C-reactive protein/albumin ratio (CRP/ALB), inflammatory markers, and parameters from the complete blood count (CBC) in patients with inflammatory bowel disease (IBD) and their associations with disease activity." (PMID 32655630, 2020). "Initial screening would usually include baseline blood tests (including C-reactive protein) and stool tests (including fecal calprotectin and culture) for exclusion of infections, celiac disease, and inflammatory bowel disease (IBD)." (PMID 30908308, 2019). "Inflammatory bowel disease was attributed as the cause of the elevated CRP in 8% of cases and the etiology of the elevated CRP could not be determined in 14% of subjects." (PMID 29855349, 2018). "Interestingly, older studies regarding CRP levels and inflammatory bowel disease have reported that the CRP response was weaker in UC than that in CD, which may be related to the fact that UC is a mucosal disease, whereas CD is a transmural disease." (PMID 26839541, 2016).
inflammatory bowel disease (continued). "Serologic markers of inflammation, such as C-reactive protein (CRP) and serum amyloid A, are strongly associated with CV disease in the general population, in addition to systemic inflammatory diseases, including RA, systemic lupus erythematosus and inflammatory bowel disease." (PMID 17425804, 2007). "C‐reactive Protein (CRP), an acute‐phase protein primarily synthesized by hepatocytes, is widely recognized as a valuable clinical biomarker for the diagnosis and monitoring of inflammatory bowel disease (IBD)." (PMID 41244339, 2025). "HERV-W envelope protein (synctin 1) has been shown to upregulate C-reactive protein (CRP) expression, which is a well-recognized biomarker of inflammation in inflammatory bowel disease." (PMID 40333136, 2025). "Previous studies have revealed that SAA may be a better biomarker of disease activity in inflammatory bowel disease (IBD) compared to C-reactive protein (CRP)." (PMID 38256249, 2024). "This microdeletion was reported in a case of infantile onset inflammatory bowel disease (IBD), severe perianal lesions, hepatosplenomegaly, and high C-reactive protein levels." (PMID 39125844, 2024). "HR: Hazard ratio, CI: confidence interval; OR: odd ratio; IBD: inflammatory bowel disease; BMI: body mass index; ESR: erythrocyte sedimentation rate; CRP: C-reactive protein." (PMID 38658864, 2024). "Several inflammatory biomarkers, including CRP, serum amyloid, TNF‐α, interleukin IL‐6, IL‐8, IL‐17A, and calprotectin are significantly increased in inflammatory bowel disease patients." (PMID 39494478, 2024). "Inflammatory bowel disease patients with low SMI were more likely to have low muscle mass; they also had high CRP and ESR, reflecting the serious chronic and persistent inflammation." (PMID 36262103, 2023). "High sensitivity C-reactive protein (hs-CRP) has attracted interest in UC in recent years due to its high sensitivity and accuracy, and its relationship with the clinical and even EA of inflammatory bowel disease (IBD)." (PMID 36572872, 2022). "Generally, in inflammatory bowel disease (IBD), CRP rises periodically along with symptoms and drops after successful prednisolone and metronidazole treatment, regardless of the organ affected." (PMID 36290272, 2022). "Our objective was to determine if patients who later develop inflammatory bowel disease (IBD) show signs of increased inflammatory activity in plasma measured with high sensitivity C-reactive protein (CRP), calprotectin, and albumin before the clinical onset of IBD." (PMID 36777274, 2021). "Although serum amyloid A protein (SAA) is mainly secreted from the liver, similar to CRP, SAA is reported to be more effective than CRP in diseases other than inflammatory bowel disease (IBD)." (PMID 32245401, 2020). "Patients with inflammatory bowel disease (IBD) had higher VAS (P = 0.03), CRP (P = 0.0009), and IL-6 (P = 0.0003) levels." (PMID 28053373, 2016). "CRP is a valuable inflammatory marker in inflammatory bowel disease (IBD), especially CD." (PMID 23058104, 2012). "Leucine-rich alpha- 2 glycoprotein (LRG) is a novel serum marker for inflammatory bowel disease (IBD) and has been recently reported to be more accurate than CRP as a marker of endoscopic severity and might be equivalent to Fcal." (PMID 40355822, 2025). "Clinical activity was assessed using the Simple Clinical Colitis Activity Index (SCCAI), quality of life using the Inflammatory Bowel Disease Questionnaire (IBDQ-32), and inflammatory status using serum interleukin-18 (IL-18), C-reactive protein (CRP), and erythrocyte sedimentation rate (ESR)." (PMID 41235106, 2025). "Although CRP is the most commonly used biomarker in the clinical management of inflammatory bowel disease, it is a non-specific marker that reflects systemic inflammation." (PMID 40130137, 2025).